ENSG00000275146
Gene: Small nucleolar RNA gene on chromosome 11 (93,721,542 to 93,721,621, forward strand). Ensembl gene ENSG00000275146.
Gene Ontology:
Biological process: RNA processing
Cellular component: nucleolus
Homologues: Orthologues: rat LOC120100395 (85% identical), rat LOC120094475 (84% identical), mouse Gm24339 (81% identical).